GSDMD (gasdermin D)
Diseases named in the same sentence as GSDMD in open-access papers (continued):
Sharing a sentence is not in itself a finding about the gene and the disease.
cardiovascular diseases (10 papers, 2021 to 2025). "Gasdermin D (GSDMD) and the pyroptosis it mediates are importantly involved in cardiovascular diseases (CVDs)." (PMID 40045452, 2025). "GSDMD participates in the development of multiple cardiovascular diseases by mediating pyroptosis in different cellular components of the cardiovascular system." (PMID 39253076, 2024). "Gasdermin D (GSDMD) has been reported to exert pyroptosis and play a critical role in the pathophysiology of many cardiovascular diseases." (PMID 38906863, 2024). "The involvement of GSDMD-mediated pyroptosis in cardiovascular diseases is well-documented." (PMID 38906863, 2024). "Recent studies have highlighted pyroptosis-related molecules—particularly gasdermin D (GSDMD), interleukin-1β (IL-1β), and interleukin-18 (IL-18)—as potential biomarkers for cardiovascular diseases." (PMID 40832143, 2025). "Although a few studies reported that circRNAs, such as circ_0138959, circ_003564, and circ-Katnal1, might have a regulatory role on GSDMD, circRNA regulation of GSDMD and pyroptosis has not been reported in cardiovascular diseases." (PMID 37498354, 2023).
kidney diseases (10 papers, 2021 to 2025). "Moreover, recent studies have indicated that GSDMD-dependent pyroptosis is also associated with kidney diseases, especially AKI21–23; hence, pyroptosis has become the focus of considerable kidney disease research." (PMID 33589596, 2021). "GSDMD mediates pyroptosis levels in renal diseases and inhibits GSDMD levels to alleviate renal injury." (PMID 39040854, 2024). "Protein levels of SCAP, FASN, PLIN2, NLRP3, and GSDMD were higher in fibrotic human kidney tissue samples, likely indicating that DNL could be associated with kidney disease." (PMID 38051585, 2023). "We detected the expression of Cx43 and GSDMD in human kidney diseases." (PMID 35641484, 2022). "Recent studies on the GSDMs family suggested that both GSDMD and GSDME were the executive proteins of pyroptosis, which played an important role in the development of renal diseases." (PMID 38388468, 2024).
Neurological diseases (7 papers, 2021 to 2025). "These researches indicate that GSDMD mediated-pyroptosis have played a critical role in neuroinflammation and nervous system diseases." (PMID 34721422, 2021). "Inhibiting GSDMD has exhibited promising neuroprotective effects in some neurological disorders." (PMID 37612735, 2023).
infectious disease (5 papers, 2023 to 2025). A disorder directly resulting from the presence and activity of a microbial, viral, or parasitic agent in humans. "In non-infectious diseases, GSDMD activation is primarily driven by DAMPs released from injured tissues, dynamically influencing parenchymal cells and circulating or resident immune cells to induce inflammatory tissue damage." (PMID 39994107, 2025). "In various infectious diseases, GSDMD-mediated pyroptosis amplifies inflammatory responses, in diverse cell types." (PMID 39994107, 2025). "Inflammasomes are signaling platforms that are activated in response to infectious diseases or chronic sterile inflammation and induce inflammation via triggering IL-1β and IL-18 or inducing pyroptosis via gasdermin-d (GSDMD)." (PMID 38026692, 2023). "GSDMD has emerged as a potential novel biomarker for the diagnosis of non-infectious diseases." (PMID 38002346, 2023). "Activation of GSDMD has been identified in many non-infectious diseases." (PMID 37305383, 2023).
neurodegenerative disease (5 papers, 2023 to 2025). A disorder of the central nervous system characterized by gradual and progressive loss of neural tissue and neurologic function. "GSDMD-mediated pyroptosis has also been implicated in the pathogenesis of Parkinson’s disease (PD), the second most common neurodegenerative disease characterized by the presence of lewy bodies rich in α-synuclein aggregates, loss of dopaminergic neurons, and motor dysfunction." (PMID 37275856, 2023). "Changes in GSDMD have also been found in the blood of PD patients, suggesting that inhibition of GSDMD may alleviate neurodegenerative diseases." (PMID 39710713, 2024). "These recent findings suggest the role of GSDMD in neurodegenerative diseases." (PMID 39253076, 2024). "In neurodegenerative diseases and CNS inflammation-related disorders, the NLRP3 inflammasome and its mediated activation of GSDMD play significant roles and have become a major focus of research." (PMID 40552323, 2025). "In cerebral ischemia and neurodegenerative diseases, cytosolic double-stranded DNA (dsDNA) activates the cyclic GMP-AMP synthase (cGAS) signaling pathway in microglia, promoting the expression of (Absent in melanoma 2) AIM-2/ NLRP3 and GSDMD, which leads to cell polarization and pyroptosis." (PMID 39994107, 2025).
metabolic disease (4 papers, 2021 to 2025). A congenital disorder (due to inherited enzyme abnormality) or acquired (due to failure of a metabolically important organ) disorder resulting from an abnormal metabolic process. "And our study confirms that GSDMD deficiency leads to metabolic disorders during neural stem cell development by affecting the way mitochondria metabolize energy." (PMID 39033542, 2024). "GSDMD is a critical effector of pyroptosis, and studies have demonstrated that excessive uncontrolled pyroptosis is implicated in the pathogenesis of metabolic disease." (PMID 36065376, 2022). "Studies have shown that GSDMD actively mediates the pathogenesis of inflammatory, infectious, and metabolic diseases." (PMID 40439590, 2025).
retinopathy (4 papers, 2023 to 2025). "Using an oxygen-induced retinopathy mouse model, we have demonstrated that GSDMD-KO largely prevents both phases of ROP as GSDMD-KO mice had decreased retinal vasoobliteration and improved retinal vascularization." (PMID 36599874, 2023).
heart disease (3 papers, 2022 to 2025). "The expressions of pyroptosis-related NLRP3, GSDMD, caspase-1, IL-1β, and IL-18 in these heart disease patients were elevated." (PMID 35647057, 2022). "We found that DOX treatment induces an increase in GSDMD levels, suggesting that GSDMD may be involved in the occurrence of tumor-related heart disease and is mainly regulated by the caspase-11/GSDMD signaling pathway." (PMID 36289195, 2022). "In addition to the well‐established role of pyroptosis in IHD, recent studies increasingly demonstrate that GSDMD‐mediated pyroptosis also plays a crucial role in the development of heart failure in nonischaemic heart disease." (PMID 39929748, 2025).
kidney (3 papers, 2021 to 2023). "We hypothesized that GSDMD might play a similar role in acute kidney injury and acute colitis through a similar mechanism." (PMID 34721422, 2021).
gastrointestinal disease (2 papers, 2021 to 2022). A disease that occurs in the gastrointestinal system, excluding the hepatobiliary system. "Our results indicate for the first time that terazosin significantly activates Pgk1-mediated protective defenses against gastrointestinal disease in an AKT- or Cas1/GSDMD-related pyroptosis manner." (PMID 35008842, 2021).
intestinal bacterial infections (1 paper, 2024). "GSDMD, a key mediator of pyroptosis downstream of the inflammasome, significantly affects intestinal mucosal immunity and the onset of intestinal disease." (PMID 38807373, 2024).
GSDMD also shares sentences with these, for which no sentence is quoted: acute myocardial infarction (8 papers); non-alcoholic steatohepatitis (6); nonalcoholic fatty liver disease (5); Seizure (5); Autoimmunity (4); Encephalopathy (4); fibrosis (4); acute lung injury (3); ileitis (3); shigellosis (3); atopic dermatitis (2); cognitive disorder (2); dementia (2); dyslipidemia (2); encephalomyelitis (2); esophageal cancer (2); gastric tumors (2); kidney inflammation (2); metastatic melanoma (2); pancreatic ductal adenocarcinoma (2); parasite infection (2); thyroid (2); uterine carcinosarcoma (2); adenocarcinoma (1); age-related hearing loss (1); AIDS (1); alopecia areata (1); amyloid (1); ankylosing spondylitis (1); anxiety disorder (1).
A further 82 diseases each share a sentence with GSDMD in 1 paper.